SYP (synaptophysin)
Diseases named in the same sentence as SYP in open-access papers (continued):
Sharing a sentence is not in itself a finding about the gene and the disease.
tumor (continued). "The tumor cells also showed positive staining for CK8 (Fig 4C3) but not E-cadherin, CK5, p63, or synaptophysin (Fig 4C5-8)." (PMID 30677079, 2019). "The tumor cells were positive for cytokeratin, nuclear/membranous β-catenin, CD10, and CD56 and were negative for chromogranin A, synaptophysin, progesterone receptor, vimentin, and Bcl-10." (PMID 31784920, 2019). "In contrast, two tumours without NANOG suppression (H646 and H627) still showed induction of SYP and NSE, suggesting alternative pathways towards NE properties." (PMID 30820548, 2019). "Immunohistochemical staining showed that the tumor cells were negative for AE1/AE3, CK18, CK7, CK19, Hepatocyte Paraffin-1, Glypican-3, Arginase-1, CD56, Chromogranin A, Synaptophysin, Vimentin, and Carcinoembryonic antigen." (PMID 31488173, 2019). "The tumor is negative for EMA, cytokeratin 7, cytokeratin 20, chromogranin A, synaptophysin, S-100 protein, HMB-45, desmin, SMA, EBV, CD117, DOG1, CD23, CD21, clusterin, MDM2, CD34, D240, and ERG." (PMID 31623602, 2019). "Although the primary tumor derived from PC3-652 was weakly positive compared to PC3-vector control by immunostaining for NED markers, chromogranin A (CGA) and synaptophysin (SYP), the kidney metastasis was negative for these markers." (PMID 29721191, 2018). "Immunostaines for RCC, CD10, CK20, chromogranin A, synaptophysin, TTF-1, thyroglobulin, and transthyretin were negative in the tumor cells." (PMID 30340515, 2018). "Tumor cells were positive for vimentine and EMA, and were negative for SMA, TTF-1, Chromogranin A, synaptophysin." (PMID 30285886, 2018). "The tumor cells were negative for CK20, synaptophysin, chromogranin A, transthyretin, TTF-1, RCC, thyroglobulin, and CD10." (PMID 30340515, 2018). "Unlike ENI, specimen tumor cells in this case were positive for GFAP and S100, but not synaptophysin and NeuN, which did not support the diagnosis of ENI." (PMID 28320419, 2017). "Immunohistochemically, tumor cells were positive for cytokeratin (CK)-AE1/3, CK7, TTF-1, CEA, calcitonin, synaptophysin, and chromogranin A, but negative for CK20, Napsin A, Pax8, and p40." (PMID 29237502, 2017). "The tumor included a heterogeneous population of GFAP and synaptophysin immunopositive cells and did not stain for either NeuN or IDH1 R132H." (PMID 29872694, 2017). "The tumor was positive for AE1/AE3 and negative for CD3, CD56, CD79a, synaptophysin, and chromogranin A expression." (PMID 27818885, 2016). "Immunohistochemically, the resected specimen revealed that the tumor and the lymph node metastasis were positive for chromogranin A and CD56 and negative for synaptophysin." (PMID 27457078, 2016). "On the microscopic pathology examination, the tumor was proven to be a small cell carcinoma and immunohistochemically the tumor was positive for CD56, synaptophysin, and CK, but with negative PSA." (PMID 27413569, 2016). "The immunophenotype (AE1/AE3-, vimentin+, PAX8-, alpha-inhibin+, Melan-A+, synaptophysin+ and NSE+) did not support a renal origin of the tumor." (PMID 27094262, 2016). "The tumor was strongly immuno-reactive for GFAP, SMARCB/INI-1 was preserved, and the tumor was negative for chromogranin, synaptophysin, Cam 5.2, EMA, desmin, myogenin, neurofilament and mutant-specific IDH1 (R132H)." (PMID 27582545, 2016). "Otherwise, this tumor was positive for Cam5.2 and MAP-2 and negative for EMA, GFAP and synaptophysin." (PMID 27229317, 2016). "The tumor cells were immunoreactive for pancytokeratin, CD56, focal synaptophysin, and thyroid transcription factor- (TTF-) 1 but negative for CD20, leukocyte common antigen, and S100." (PMID 26137338, 2015).
tumor (continued). "In this case, the tumor cells were proven chromophobic by Pearse’s PAS stain, showing immunopositivity for PRL, chromogranin-A, and synaptophysin but no immunoreactivity to S-100 protein, vimentin, and GFAP." (PMID 26228535, 2015). "On immunohistochemistry, the tumor cells are typically negative for epithelial markers (i.e., EMA and cytokeratins), chromogranin A, synaptophysin, S-100, HMB45, and Melan-A." (PMID 25587475, 2014). "Immunohistochemically, the tumor cells were positive for synaptophysin and CD56 and negative for chromogranin A. Only a few tumor cells were positive Ki-67." (PMID 25392779, 2014). "Immunohistochemically >80% of the invasive tumor cells showed moderate granular chromogranin A expression and showed moderate membranous expression of CD117, whereas synaptophysin, NSE, and CD56 were negative." (PMID 24701575, 2014). "Immunohistochemical studies demonstrated tumor positivity for AE1/AE3 in a dot-like pattern, synaptophysin, and chromogranin and were negative for CD45, S100, and myogenin." (PMID 25057271, 2014). "In general, the neoplastic cells of an NET are immunopositive for all the neuroendocrine markers, while the tumor cells of an SPN are positive for NSE and CD56 and mostly negative for synaptophysin and chromogranin." (PMID 24137427, 2013). "The immunohistochemistry analysis revealed that the tumor cells were positive for NSE, CD56, β-catenin and CD10 and negative for chromogranin, synaptophysin and trypsin." (PMID 24137427, 2013). "An immunohistochemical analysis showed that the tumor cells were positive for neuron specific enolase (NSE), CD56, chromogranin, synaptophysin, β-catenin and CD10 and negative for trypsin." (PMID 24137427, 2013). "In our case, the tumor cells were positive for vimentin, CD10, and pancytokeratin, but negative for CK7, CEA, chromogranin, synaptophysin and CD68." (PMID 23305230, 2013). "In the present case, tumor cells showed marked cytoplasmic staining for GFAP and S-100 protein, whereas immunoreactivity for CK, EMA, chromogranin, EGFR and synaptophysin were all negative." (PMID 24137352, 2013). "Immunohistochemically, the tumor cells were widely positive for vimentin, CD56, CD99 and focally positive for synaptophysin, CD10, progesterone receptor, desmin and CD34, but negative for EMA, cytokeratin, estrogen receptor, S-100 and myoglobin." (PMID 23217062, 2012). "Immunohistochemically, the tumor cells were positive for vimentin, CD56, synaptophysin (focal) but negative for EMA, cytokeratin, S-100." (PMID 23217062, 2012). "The tumor in our case was positive for CD56, CD99 (to our knowledge the second reported case), synaptophysin and negative for EMA and cytokeratin." (PMID 23217062, 2012). "Immunohistochemically, the tumor cells were widely positive for vimentin, CD56, CD99 and focally positive for synaptophysin, CD10, progesterone receptor, desmin and CD34, but negative for EMA, cytokeratin, estrogen receptor, S-100, GFAP and myoglobin." (PMID 23217062, 2012). "This tumor displayed CD10 negative, chromogranin positive, synaptophysin positive, and vimentin weak positive findings on immunohistochemistry which led to a pathological diagnosis of well differentiated benign cystic PET." (PMID 21771323, 2011). "The tumor contained serous fluid and pathological diagnosis of cystic PET was made according to immunohistochemistry findings which showed chromogranin, synaptophysin positive findings and CD10 negative findings." (PMID 21771323, 2011). "In the present case, samples were positive for chromogranin A and synaptophysin, and had a Ki67 index of 20%–30%, but could not be categorized as having MiNEN because NEC accounted for only 20% of the total tumor." (PMID 40567873, 2026). "Indeed, the neuronal markers NeuN, neurofilament protein, and chromogranin were negative, and the tumor cells displayed mild positivity for SOX2 and focal immunoreactivity for synaptophysin." (PMID 39492623, 2025).
tumor (continued). "Moreover, the tumor was partly positive for S-100P, CD56, CD68 and LCA, while negative for chromogranin A, synaptophysin, Myo D1, CD34, calretinin and BCOR." (PMID 39930783, 2025). "Immunohistochemical markers such as neuronal specific enolase, synaptophysin, chromogranin A and CD56 are not always positive in GCAs, and tumours with absent neuroendocrine immunoreactivity may exist." (PMID 40729214, 2024). "IHC analysis revealed that SYP is absent in all samples, whereas weak, focal CD56 and INSM1 positive staining was detected in both the patient lymph node metastatic biopsy and CU-PC01 PDX tumours." (PMID 38667288, 2024). "Additionally, the tumor was positive for CK5, AE1/AE3+CK8/18, p63, vimentin, E-cadherin, and synaptophysin, while estrogen receptor staining was negative." (PMID 39765541, 2024). "Tumor cells of another case are negative for CD99, WT-1, S100, synaptophysin, and chromogranin." (PMID 38854270, 2024). "Immunohistochemistry of liver metastatic biopsies and PDX tumor showed lack of expression of typical PCa (e.g., AR, PSA, PSAP, ERG) or neuroendocrine markers (synaptophysin), compatible with double-negative CRPC, but was positive for nuclear β-catenin expression, keratin 7 and 34βE12." (PMID 38907236, 2024). "Tumor cells exhibited a uniform strong cytoplasmic immunoreactivity for ALK, expressed AR and NKX3.1 but were negative for the neuroendocrine marker synaptophysin." (PMID 36337169, 2022). "(Immunohistochemical stains showed that the tumor cells were positive for desmin and TFE3, while negative for pancytokeratin, CAM5.2, EMA, chromogranin, synaptophysin, NSE, CD45, SMA, HHF35, myogenin, CD117, DOG1, MUC4, S100, SOX10, HMB45, Melan-A, CD31, ERG, TLE1, STAT6, and Cathepsin-K)." (PMID 35001360, 2022). "The tumor strongly expressed OLIG2 and synaptophysin but not neurofilament nor chromogranin A." (PMID 32605662, 2020). "Tumor cells strongly expressed OLIG2 and to a lesser extent synaptophysin but not GFAP nor CD34." (PMID 32605662, 2020). "However, one tumour (H643) showed induction of luminal markers (CK8 and CK18) without the NE markers SYP and NSE." (PMID 30820548, 2019). "Immunohistochemically, the tumor was strongly positive for keratin 7 (CK7) and pankeratin AE1/AE3, and alpha 1 antichymotrypsin; negative for synaptophysin and chromogranin A, CDx2, CK20, S100, carcinoembryonic antigen (CEA), MUC 2, MUC5AC, and somatostatin; and in part positive for CA19-9." (PMID 29145864, 2017). "The tumor cells were immunoreactive for cytokeratin 7 (CK7), thyroid transcription factor-1 (TTF-1), and napsin A and were negative for CD20, CDX2, P63, chromogranin, synaptophysin, and CD56." (PMID 26425638, 2015). "Immunohistochemistry the tumor was positive for vimentin, focal positivity with AE1-AE3 CK, CK5 and high molecular weight cytokeratin and negative for EMA, CD34, desmin, myosin, CroA, synaptophysin and S100." (PMID 23886403, 2013). "Immunohistochemistry the tumor was positive for vimentin, smooth muscle actin and Ki-67; focal positivity with AE1-AE3 CK, CK5 and high molecular weight cytokeratin and negative for EMA, CD34, desmin, myosin, CroA, synaptophysin and S100." (PMID 23886403, 2013). "In Prostatic stromal sarcoma (PSS) unlike the PES, immunohistochemically, the tumour cells are widely positive for vimentin, CD56, CD99 and focally positive for synaptophysin, CD10, progesterone receptor, desmin and CD34, but negative for EMA, cytokeratin, estrogen receptor, S-100 and myoglobin." (PMID 23886403, 2013). "Immunostaining further revealed that the tumor cells expressed smooth muscle actin, h-caldesmon, muscle specific actin (HHF-35), but not cytokeratin, epithelial membrane antigen, synaptophysin, or chromogranin A. Based on these findings, a diagnosis of primary pulmonary glomus tumor was established." (PMID 23050181, 2012). "No reactivity could be obtained in any tumor for cytokeratins, HMB 45, myogenin, CD 31, CD 34, factor VIII, and synaptophysin." (PMID 18593459, 2008).
tumor (continued). "Most notably, the tumor was found to be negative for Brachyury, CD68, SRY-box transcription factor 10 (SOX10), HMB45, glial fibrillary acidic protein, oligodendrocyte transcription factor 2, anaplastic lymphoma kinase, desmin, CD117, synaptophysin, and neurofilament." (PMID 37598295, 2023). "Immunohistochemical staining showed that the tumor cells were negative for AE1/AE3, CK18, CK7, Hepatocyte Paraffin-1(Hep Par-1), Glypican-3 (GPC-3), Arginase-1 (ARG-1), CD56, Chromogranin A (CgA), Synaptophysin (Syn), Vimentin, and Carcinoembryonic antigen (CEA)." (PMID 31488173, 2019).
adenocarcinoma (75 papers, 2007 to 2026). A common cancer characterized by the presence of malignant glandular cells. "When considering all 29 adenocarcinomas, there was a strong association between CgA protein and synaptophysin protein (r = 0.7, p < 0.01), and CgA protein and CgA mRNA (r = 0.6, p < 0.01))." (PMID 28980157, 2018). "Moreover, LCM-derived RNA-seq analysis confirmed that these KRT-8-high, SYP-low adenocarcinoma cells expressed gene signatures associated with epithelial differentiation and were depleted of neural lineage–related gene expression." (PMID 37546702, 2023). "Macroscopically, adenocarcinoma cells were present on both sides of the NET, while microscopically, some adenocarcinoma cells were positive for neuroendocrine markers (synaptophysin and chromogranin A)." (PMID 40511448, 2025). "The study excluded MiNEN and synaptophysin staining adenocarcinoma cases and including only digestive primaries, hence resulting in a large and separate digestive NEC and NET G3 cohort." (PMID 40382522, 2025). "These AR-positive, SYP-positive tumors (often referred to as amphicrine, example shown SI Appendix) have adenocarcinoma histology and clinically behave differently than bona fide NEPC tumors." (PMID 38968122, 2024). "Partial neuroendocrine features (positive synaptophysin expression with maintained AR expression and an adenocarcinoma morphology) were noted in primary PCa from one patient (Patient 7) and in the metastasis of another patient (Patient 6)." (PMID 35220606, 2022). "The fifth and last group summarized 12/239 (5%) adenocarcinomas with diffuse and intense synaptophysin staining of almost all cells of the neoplastic glands." (PMID 34680258, 2021). "In the next step, we compared the survival data of synaptophysin-expressing conventional adenocarcinomas with those of true colorectal MANECs." (PMID 34680258, 2021). "We found that the luminal-like malignant phenotype of NE cells (K5−K18+SYP+) is mainly detected in adenocarcinomas." (PMID 33328604, 2020). "These include neuroendocrine markers in UWG01CTC such as chromogranin A, CD56, and synaptophysin, and cytokeratin markers seen in adenocarcinomas in UWG02CTC." (PMID 31953491, 2020). "Synaptophysin was expressed in the cytoplasm of the positive cells, and the staining intensity of synaptophysin was strong in the NETs, and weaker in the NECs and adenocarcinomas." (PMID 28980157, 2018). "Pathological examination revealed poorly differentiated adenocarcinoma with neuroendocrine features of positive synaptophysin and chromogranin-A expressions." (PMID 30458812, 2018). "Overall, PLum-C orthotopic adenocarcinoma tumors displayed a glandular luminal phenotype with relatively frequent occurrences of CK8/Synaptophysin double positive cells and rare occurrences of basal cells." (PMID 22022528, 2011). "To further confirm whether the NEPC and adenocarcinoma markers are expressed in distinct cells, we performed immunofluorescence to costain for the neuroendocrine markers SYP and INSM1 along with the epithelial marker CK8." (PMID 37546702, 2023). "The true MANECs showed a significantly worse clinical outcome (OS: p < 0.001; DSS: p < 0.001; DFS: p < 0.001) compared to the group of diffuse synaptophysin-expressing conventional adenocarcinomas (e.g., mean DFS: 16.98 months vs. 77.81 months) in univariate analyses." (PMID 34680258, 2021). "Expression of synaptophysin was observed in nine of 29 (31%) adenocarcinomas, and of these the marker was expressed in three of ten (30%) intestinal type adenocarcinomas, four of 15 (27%) diffuse type adenocarcinomas, and two of four (50%) mixed/indeterminate type adenocarcinomas." (PMID 28980157, 2018). "Biopsies from the anal canal tumor, swollen lymph node, and Paget lesion all showed poorly differentiated adenocarcinoma with neuroendocrine features expressing synaptophysin and chromogranin A. Serum CEA and NSE levels were high, 809.4 ng/ml and 85.8 ng/ml, respectively." (PMID 30458812, 2018).